NSD1 (nuclear receptor binding SET domain protein 1)
Diseases named in the same sentence as NSD1 in open-access papers (continued):
Sharing a sentence is not in itself a finding about the gene and the disease.
laryngeal tumors (7 papers, 2017 to 2023). "Of those, we found anatomic and genetic differences among tumors, with CASP8 mutations almost solely in the oral cavity and NSD1 predominant in laryngeal tumors." (PMID 37081260, 2023). "We therefore analyzed the mutational profile of NSD1 in the complete TCGA set of 116 laryngeal tumors for which at least mutational data were available among a total of 526 SCCHN cases." (PMID 29176703, 2017). "The peculiar genomic characteristics also include loss‐of‐function alterations of the chromatin modifier NSD1, WNT pathway genes AJUBA and FAT1, and activation of oxidative stress factor NFE2L2, mainly in laryngeal tumours." (PMID 37322598, 2023). "On the other hand, majority of the laryngeal tumours harboured alterations in Wnt pathway genes, a chromatin modifier (NSD1) and activation of NFE2L2, an oxidative stress factor." (PMID 37322598, 2023). "Damaging mutations in NSD1 and NSD2 were reported to define a subset of stage 3 and 4 laryngeal tumors with favorable prognosis." (PMID 33588906, 2021). "NSD1 mutations correlated with improved survival in HPV(−) tumors, consistent with previously published work in laryngeal tumors." (PMID 31321084, 2019). "Although NSD1 mutations were detected in oral tumors, the association of NSD1 mutation with better OS and RFS was specific to laryngeal tumors, suggesting a biological difference between tumor subsites." (PMID 29176703, 2017). "The results were specific to mutation rather than altered gene expression, as among cases with NSD1 and NSD2 wild-type alleles in oropharynx and hypopharynx tumors and laryngeal tumors, NSD1 mRNA expression levels did not predict survival." (PMID 29176703, 2017).
prostate carcinoma (7 papers, 2012 to 2024). A carcinoma that arises from epithelial cells of the prostate gland. "Altogether, we identify NSD2 as a novel subunit of the AR neo-enhanceosome that wires prostate cancer gene expression programs, positioning NSD1/2 as viable paralog co-targets in advanced prostate cancer." (PMID 38464251, 2024). "Altogether, we characterize NSD2 as an essential AR neo-enhanceosome subunit that enables its oncogenic activity, and position NSD1/2 as viable co-targets in advanced prostate cancer." (PMID 39251788, 2024). "NSD2 inactivation also engenders increased dependency on the NSD1 paralog, and a dual NSD1/2 PROTAC degrader is preferentially cytotoxic in AR-dependent prostate cancer models." (PMID 39251788, 2024). "Concordantly, a dual NSD1/2 PROTAC degrader, called LLC0150, was preferentially cytotoxic in AR-dependent prostate cancer as well as NSD2-altered hematologic malignancies." (PMID 38464251, 2024).
laryngeal carcinoma (6 papers, 2017 to 2024). Carcinoma that arises from the laryngeal epithelium. "In laryngeal cancers, loss-of-function mutations in NSD1 were shown to be a favorable prognostic biomarker." (PMID 31321084, 2019). "In a recent study, loss-of-function mutations in NSD1 were shown to be a favorable prognostic biomarker in laryngeal cancers, which are almost uniformly HPV(−) and strongly associated with tobacco and alcohol use." (PMID 31321084, 2019). "Inactivating mutations in NSD1 were shown to be a favorable prognostic biomarker in laryngeal cancers." (PMID 31321084, 2019). "Subsequent validation in an independent set of 63 laryngeal cancer samples again demonstrated that mutations in NSD1 or NSD2 are independent favorable prognostic biomarkers for laryngeal cancer." (PMID 29176703, 2017). "This analysis identified two distinct clusters of laryngeal cancer, associated with strong prognostic value, and showed that mutations in the genes NSD1 and NSD2 entirely segregated to the cluster with favorable prognosis." (PMID 29176703, 2017). "Altogether, these observations that indicated loss-of-function mutations in NSD1 or NSD2 are associated with better prognosis specifically in laryngeal cancer." (PMID 29176703, 2017). "This is suggestive of possible regulation by NSD1 of not only ULK1 at the transcriptional level but also of its downstream target Beclin-1 in laryngeal cancer cell types." (PMID 38346948, 2024). "NSD1- or histone H3-mutated tumors have been found to constitute a hypomethylated subset within HPVneg HNSCC while NSD1 and NSD2 mutations have been associated with favorable prognosis in laryngeal cancers." (PMID 35664801, 2022). "Classification of the TCGA HPV(−) cohort by site revealed that laryngeal cancers were overrepresented amongst those with mutant NSD1: 25% of HPV(−) tumors arose in the larynx but almost 60% of HPV(−) tumors with NSD1 mutations occurred in the larynx." (PMID 31321084, 2019). "Moreover, the overexpression of PIP4K2B in NSD1-depleted cells leads to the restoration of proliferation levels and downstream targets of mTORC1, specifically observed in a laryngeal cancer cell line." (PMID 38539515, 2024). "In particular, while a subset of HPV-negative HNSCC, primarily laryngeal carcinoma with NSD1 loss of function mutations, has a favorable prognosis, this represents only a minority of HNSCC, while >80% HPV-negative head and neck tumors are NSD1-wild type." (PMID 37786686, 2023). "Although most common laryngeal gene mutations are found in both subclasses, better prognosis is strongly associated with damaging mutations of the methyltransferases NSD1 and NSD2, with findings confirmed in an independent validation cohort consisting of 63 laryngeal cancer patients." (PMID 29176703, 2017). "NSD1 and PIP4K2B have potential as targets for laryngeal cancer therapy and future cancer drug development." (PMID 38539515, 2024). "In conclusion, our findings implicate PIP4K2B as a novel NSD1-dependent protein in HNSCC, suggesting its potential significance for laryngeal cancer cell survival." (PMID 38539515, 2024). "In sum, this work nominates NSD1 and NSD2 as rapidly exploitable prognostic biomarkers and targets for functional scrutiny in laryngeal cancers." (PMID 29176703, 2017). "Our PIP4K2B rescue experiment further highlighted that the NSD1-mediated inhibition of cell growth in the JHU011 cell line could be rescued by PIP4K2B in short-term assays, suggesting a potential dependency of laryngeal carcinoma cells on PIP4K2B for supporting cell growth." (PMID 38539515, 2024).
Macrocephaly (5 papers, 2007 to 2025). Occipitofrontal (head) circumference greater than 97th centile compared to appropriate, age matched, sex-matched normal standards. "Genomic DNA from 88 unrelated individuals with autism spectrum disorders and macrocephaly was screened for intragenic NSD1 mutations by sequencing analysis." (PMID 18001468, 2007). "We cannot exclude a hypomorphic effect for the variants identified in S15–S17 on NSD1 function that might underlie or contribute to the isolated macrocephaly observed in the three patients and their transmitting parents." (PMID 36421837, 2022). "We screened NSD1 by direct sequencing in 88 subjects with autism spectrum disorder and macrocephaly." (PMID 18001468, 2007). "In conclusion, no NSD1 mutations, 5q35 microdeletions or partial NSD1 deletions were identified in this large sample of patients with autism spectrum disorders and macrocephaly." (PMID 18001468, 2007).
autism (4 papers, 2007 to 2024). Persistent deficits in social interaction and communication and interaction as well as a markedly restricted repertoire of activity and interest as well as repetitive patterns of behavior. "Significantly greater than expected number of rare variants were detected in 5 of the 101 tested autism-linked genes: AUTS2, NHS, NSD1, SLC9A9, and VPS13B." (PMID 31134136, 2019). "Rare variant analysis on a cohort level confirmed the association of five genes with autism (AUTS2, NHS, NSD1, SLC9A9, and VPS13)." (PMID 31134136, 2019).
Beckwith-Wiedemann syndrome (4 papers, 2017 to 2023). Beckwith-Wiedemann syndrome (BWS) is a genetic disorder characterized by overgrowth, tumor predisposition and congenital malformations. "In a more clinical perspective, the discovery of NSD1 mutations in Beckwith-Wiedemann syndrome (BWS), an imprinted and congenital overgrowth syndrome, could indicate a causal link between NSD1 LoF, alterations to parental imprints and overgrowth phenotype." (PMID 33916664, 2021). "Indeed, NSD1 mutations have also been observed in unexplained cases of a congenital overgrowth syndrome known as Beckwith-Wiedemann syndrome (BWS), which is characterized by macroglossia, visceromegaly, umbilical hernia, abdominal wall defect and a predisposition to cancer." (PMID 36230787, 2022).
epilepsy (4 papers, 2020 to 2023). A brain disorder characterized by episodes of abnormally increased neuronal discharge resulting in transient episodes of sensory or motor neurological dysfunction, or psychic dysfunction. "Indeed, we report for the first time post-operative seizure outcomes for six genetic causes of epilepsy: COL4A1, GRIN2B, NEXMIF, NSD1, SCN2A and SLC9A6." (PMID 37264783, 2023). "They observed that six (5.9%) patients with functional seizures (without comorbid epilepsy) carried pathogenic/likely pathogenic variants (deletions at 10q11.22-q11.23, 10q23.1-q23.2, distal 16p11.2, and 17p13.3, and nonsynonymous variants in NSD1 and GABRA5)." (PMID 37628589, 2023). "We observe in this first genetic investigation of PNES that six (5.88%) individuals with PNES without coexistent epilepsy carry P/LP variants (deletions at 10q11.22-q11.23, 10q23.1-q23.2, distal 16p11.2, and 17p13.3, and nonsynonymous variants in NSD1 and GABRA5)." (PMID 32938993, 2020).
erythroleukemia (4 papers, 2020 to 2023). Acute erythroid leukemia characterised by the presence of at least 50% erythroid precursors and at least 20% myeloblasts in the bone marrow. "Here, the authors report that NSD1 loss blocks erythroid differentiation which leads to an erythroleukemia-like disease in mice by impairing GATA1-induced target gene activation." (PMID 32533074, 2020). "Inactivation of NSD1 has been shown to induce erythroleukemia in mice, yet its role in human erythropoiesis is unexplored." (PMID 37174702, 2023). "Remarkably, Vav-iCre-controlled inactivation of the Nsd1 (Nsd1-/-) gene in the hematopoietic system of the mouse induced a fully penetrant erythroleukemia-like disease characterized by anemia, thrombocytopenia and multi-organ erythroblast infiltration." (PMID 33235911, 2020). "In contrast to Gata11.05/+ mice, Nsd1−/− mice developed a fully penetrant erythroleukemia-like phenotype after a shorter latency." (PMID 32533074, 2020). "Ablation of Nsd1 in the hematopoietic system of mice induces a transplantable erythroleukemia." (PMID 32533074, 2020).
Kabuki syndrome (4 papers, 2019 to 2025). Kabuki syndrome (KS) is a multiple congenital anomaly syndrome characterized by typical facial features, skeletal anomalies, mild to moderate intellectual disability and postnatal growth deficiency. "To further validate the specificity of the BOS DNAm signature generated, we classified three cohorts of individuals with Sotos, Weaver, and Kabuki syndromes, caused by variants in genes encoding the epigenetic regulators, NSD1, EZH2, and KMT2D, respectively." (PMID 35361921, 2022).
lung adenocarcinoma (4 papers, 2017 to 2024). A carcinoma that arises from the lung and is characterized by the presence of malignant glandular epithelial cells. "At the same time, we analyzed the mutation rates of H3K36 enzymes (including NSD1, NSD2, NSD3, ASH1L, SMYD2, SETDB2, SETD3, and SETMAR) in lung adenocarcinoma, which showed that the amplification mutation frequency of H3K36 enzymes was at a low level." (PMID 39119928, 2024). "Examples were NSD1 in HNSC, CTNNB1 in liver hepatocellular carcinoma (LIHC), and STK11 and KEAP1 in lung adenocarcinoma (LUAD)." (PMID 29125844, 2017).
renal cell carcinoma (4 papers, 2017 to 2022). "The majority of these mutant genes have been reported to associate with tumorigenesis and metastasis of cancer cells, such as TXNIP in TNBCs and NSD1 in renal cell carcinoma." (PMID 35410320, 2022). "The nuclear receptor binding SET domain protein 1 (NSD1), a histone methyltransferase, was found to be frequently mutated in the clear cell variant of renal cell carcinoma and associated with DNA hypomethylation." (PMID 29340043, 2017). "NSD1 is a histone 3 Lys 36 (H3K36) methyltransferase similar to SETD2, which is frequently mutated in the clear cell variant of renal cell carcinoma, and associated with DNA hypomethylation." (PMID 28405244, 2017).
scoliosis (4 papers, 2019 to 2024). A congenital or acquired spinal deformity characterized by lateral curvature of the spine. "The contribution of NSD1 does not seem to explain all phenotypes observed in the proband, e.g., scoliosis and craniofacial features." (PMID 36303224, 2022).
acute leukemia (3 papers, 2020 to 2025). A clonal (malignant) hematopoietic disorder with an acute onset, affecting the bone marrow and the peripheral blood. "The nuclear receptor binding SET domain protein 1 (NSD1) is recurrently mutated in human cancers including acute leukemia." (PMID 32533074, 2020).
autism spectrum disorder (3 papers, 2007 to 2025). A spectrum of developmental disorders that includes autism, and Asperger syndrome. "We screened the NSD1 gene for mutations and deletions in 88 patients with autism spectrum disorders and macrocephaly (head circumference 2 standard deviations or more above the mean)." (PMID 18001468, 2007). "Thus, the aim of this study was to assess the frequency of NSD1 mutations in cases of autism spectrum disorder associated with macrocephaly, defined as an occipitofrontal head circumference (HC) 2 SD or more above the mean." (PMID 18001468, 2007).
clear cell renal carcinoma (3 papers, 2019 to 2022). A malignant epithelial neoplasm of the kidney characterized by the presence of lipid-containing clear cells within a vascular network. "Reduced NSD1 activity has been observed in head and neck cell cancers, while abnormal DNA-promoter hypermethylation is associated with renal clear-cell carcinoma." (PMID 35888078, 2022).
colon cancer (3 papers, 2013 to 2024). "Little is known regarding the role of NSD1 in colorectal cancer; however, publicly available data indicate that NSD1 somatic alterations occur in 4% of colon cancers (source: cBioPortal; accessed January 2022)." (PMID 35158968, 2022).
esophageal cancer (3 papers, 2020 to 2024). A primary or metastatic malignant neoplasm involving the esophagus. "NSD1 loss decreases the growth of liver, breast and esophageal cancer cells, and NSD1 depletion leads to a moderate increase in sensitivity to cisplatin and carboplatin drugs." (PMID 37786686, 2023).
lung squamous cell carcinoma (3 papers, 2017 to 2022). "A similar hypomethylated tumor subtype enriched for inactivating NSD1 mutations and deletions was also found in lung squamous cell carcinoma (LUSC)." (PMID 34575025, 2021). "Here, we follow up upon our subtyping analysis to describe the NSD1 subtype and report our identification of an epigenetically and transcriptionally similar NSD1 subtype occurring in lung squamous cell carcinoma (LUSC)." (PMID 29213088, 2017). "Investigating HNSSC or lung squamous cell carcinomas revealed that mutations did not abrogate NSD1 expression in most samples." (PMID 34575025, 2021).
atrioventricular septal defect (2 papers, 2022 to 2023). "A de novo variant in NSD1 was associated with atrioventricular septal defect, a specific cardiac malformation that presented as a congenital heart disease; and, NSD1 genetic variants have been associated with congenital heart disease." (PMID 37504561, 2023).
bladder cancer (2 papers, 2015 to 2020). "One study in bladder cancer dataset, Nakshatri and colleagues observed the linking of NSD1 expression and bladder cancer stages reinforcing our findings." (PMID 32153656, 2020).
breast tumors (2 papers, 2012 to 2022). "NSD1 (nuclear receptor binding SET domain protein 1) gene silencing was associated with tamoxifen resistance in breast tumors." (PMID 22984562, 2012). "Moreover, in breast tumors, NSD1 gene silencing was associated with reduced sensitivity to tamoxifen, thereby linking NSD1 loss to therapeutic resistance." (PMID 36230787, 2022).
congenital heart disease (2 papers, 2023). A heart disease that is present at birth. "Variants in the genes that encode the H3K36 methyltransferases, NSD1, NSD2, and, ASH1L, have been linked to congenital heart disease." (PMID 37504562, 2023).
endometrial cancer (2 papers, 2020 to 2022). Primary or metastatic malignant neoplasm involving the endometrium (mucous membrane that lines the endometrial cavity). "KMT3B (NSD1) is one of the miR-181a targets, and the oncogenic role of hsa-miR-181a suggests it could be a prognostic biomarker in endometrial cancer." (PMID 35087589, 2022).
hypopharyngeal carcinoma (2 papers, 2017 to 2019). Carcinoma, predominantly squamous cell, arising from the epithelial cells of the hypopharynx. "PRB4 and NSD1 expression were significantly upregulated in hypopharyngeal carcinoma, which was confirmed in an independent cohort using IHC." (PMID 29156722, 2017). "We found that PRB4 and NSD1 were dramatically increased in hypopharyngeal carcinoma tissues compared with adjacent tissues." (PMID 29156722, 2017). "Therefore, PRB4 and NSD1 mutations might contribute to hypopharyngeal carcinoma tumorigenesis." (PMID 29156722, 2017). "We also indentify a novel epigenetically regulatory between PRB4 and NSD1 that contribute to hypopharyngeal carcinoma tumorigenesis." (PMID 29156722, 2017). "We focused on the role of PRB4 and NSD1 in hypopharyngeal carcinoma." (PMID 29156722, 2017). "Thus, the results suggest that PRB4 and NSD1 might contribute to the development of hypopharyngeal cancer." (PMID 29156722, 2017). "However, the functions of PRB4 and NSD1 (nuclear receptor binding SET domain protein 1) are not clear in hypopharyngeal carcinoma." (PMID 29156722, 2017).
melanoma (2 papers, 2012 to 2022). A malignant, usually aggressive tumor composed of atypical, neoplastic melanocytes. "The treatment based on 5AzaCdR plus TSA caused a slight decrease on NSD1 gene expression in Mel-2 melanoma cells." (PMID 22984562, 2012). "We then report the role of NSD1 in triggering tumor suppressive or promoter functions according to the tissue context and we discuss the role of NSD1 in melanoma." (PMID 36230787, 2022). "Further studies are most required to elucidate the mechanism by which NSD1 acts in the pathogenesis of melanoma." (PMID 36230787, 2022). "NSD1 expression may fluctuate to enable melanoma development and progression." (PMID 36230787, 2022). "To shed some light into a potential significant biological relevance of NSD1 in the pathogenesis of melanoma, we focused on co-expressed genes, highlighting the tumor suppressor APC as one of the top NSD1 co-expressed genes (cBioPortal.org)." (PMID 36230787, 2022). "On the verge of these elements, a more thorough study is required since the mechanism depicting NSD1′s involvement in melanoma still has not been proven and is poorly understood." (PMID 36230787, 2022). "While these analyses suggest that NSD1 expression does not influence overall survival in melanoma, given that NSD1 is an enzyme, one cannot rule out a correlation to activity than mRNA expression." (PMID 36230787, 2022). "When NSD1′s activity is altered, the H3K36 active mark will not accumulate on APC’s promoter region; therefore the expression of the tumor suppressor APC remains repressed, subsequently the Wnt/β-catenin pathway will be constantly active, which would favor melanoma progression." (PMID 36230787, 2022).